CYP2E1 (cytochrome P450 family 2 subfamily E member 1)
Diseases named in the same sentence as CYP2E1 in open-access papers (continued):
Sharing a sentence is not in itself a finding about the gene and the disease.
Obesity (continued). "In addition, Cyp2e1 knockout mice are protected against high-fat diet-induced obesity and insulin resistance and the production of proinflammatory cytokines in adipose tissue was prevented." (PMID 34360999, 2021). "In addition, Cyp2e1 regulation is affected by age, gender, genetic factors, nutrition, hormones, and pathophysiological conditions such as diabetes and obesity." (PMID 32489392, 2020). "Elevated liver CYP2E1 content is implicated in various metabolic diseases including alcoholic liver disease, nonalcoholic fatty liver disease (NAFLD)/nonalcoholic steatohepatitis (NASH), diabetes and obesity." (PMID 33255949, 2020). "Elevated hepatic CYP2E1 content is implicated in various metabolic diseases including alcoholic liver disease, nonalcoholic fatty liver disease (NAFLD)/nonalcoholic steatohepatitis (NASH), diabetes and obesity." (PMID 33255949, 2020). "Regarding clinical studies, it was suggested that obesity increases CYP2E1 activity in children." (PMID 31752434, 2019). "CYP2E1 up-regulation has been associated to obesity, fatty liver, and NASH in both humans and rodents and correlates with NAFLD severity and progression of liver steatosis to NASH: CYP2E1 up-regulation leads to enhanced ROS production, with an increase of lipid peroxidation and inflammation." (PMID 30080863, 2018). "It is still unclear why CYP2E1 activity is increased in obesity and NAFLD, even though some studies suggested the role of disturbed intra-hepatic insulin signalling and/or accumulation of some endogenous derivatives such as ketone bodies and saturated fatty acids." (PMID 28691103, 2017). "For example, the level of CYP2E1 is lower during times when the body has received adequate nutrition (i.e., the fed state) and higher during times of starvation or with disease states such as obesity." (PMID 17718406, 2006). "In contrast, robust CYP2E1 induction, lobular inflammation, low basal concentrations of hepatic GSH and NASH-associated mitochondrial dysfunction might favor APAP hepatotoxicity in obesity and NAFLD." (PMID 36713231, 2023). "However, CYP2E1 activity was not determined in the other investigations reporting a higher risk of APAP-induced liver injury in patients with obesity and NAFLD." (PMID 36713231, 2023). "In addition, CYP2E1 levels are elevated in obesity, steatosis and NASH in both humans and rodents." (PMID 34360999, 2021). "Thus, the level of CYP2E1 is under complex regulatory control, and factors in addition to alcohol consumption, such as the nutritional state, environmental exposures, obesity, diabetes, and liver disease can contribute to the large variation of P450 found in the population." (PMID 17718406, 2006). "While clearance of CYP3A4 substrates is lower in patients with obesity, drugs primarily metabolized by UGT, xanthine oxidase, N-acetyltransferase, or CYP2E1 exhibit higher clearance in individuals with obesity." (PMID 40359692, 2025). "Although the transcriptional regulation of CYP2E1 has been linked to the activities of HNF1α, HNF4α, SP1, and C/EBP, the mechanisms by which obesity and NAFLD exacerbate CYP2E1 activity requires additional studies." (PMID 32660130, 2020). "In fact, the influence of obesity on CYP450 appears to be isoenzyme specific, with a decrease of CYP3A4 activity and an increase of CYP2E1." (PMID 25027286, 2014). "For example, one pediatric study of chlorzoxazone, a CYP2E1 substrate, found that overall systemic clearance normalized to weight was significantly higher in children with versus without obesity, while the renal elimination remained unchanged." (PMID 35359853, 2022). "The increased circulating levels of ketone bodies and fatty acids observed in obesity, steatosis and NASH may induce CYP2E1 and insulin resistance." (PMID 34360999, 2021). "On one hand, the increased activity of cytochrome P450 (CYPs) (CYP2C9, CYP1A2, CYP2E1, and CYP2D6) in individuals with obesity could augment generation of toxic metabolites." (PMID 34040524, 2021).
Obesity (continued). "The greater hepatoxicity of halothane and acetaminophen in patients with obesity and NAFLD could be explained by greater CYP2E1 activity." (PMID 31531370, 2019). "Meanwhile, increased activity of CYPs (CYP2C9, CYP1A2, CYP2E1, and CYP2D6) has been found in individuals with obesity; increased CYP activity could augment toxic metabolite generation." (PMID 31531370, 2019). "CYP2E1 is induced under a variety of pathophysiological conditions such as fasting, diabetes, obesity and high fat diet, by drugs, in non-alcohol-induced steatohepatitis and by alcohol." (PMID 26501338, 2015). "Because many endogenous molecules, hormones and cytokines are deemed to regulate hepatic CYP2E1 expression and activity, sometimes with opposite effects, it is possible that CYP2E1 induction might not always occur in obesity and NAFLD." (PMID 36713231, 2023). "The CYP2E1 has been widely studied in pigs regarding boar taint, however, its relation to porcine lipid metabolism and fatness has never been explored, even if its key role in obesity and insulin resistance phenotypes has been showed in rodents and humans." (PMID 22607048, 2012). "Since CYP2E1 plays an important role in the toxicity of ethanol, drugs and carcinogens and is activated under various pathophysiological conditions such as diabetes, NASH and obesity, attempts to stimulate autophagy may be beneficial in preventing/lowering CYP2E1/ethanol liver injury." (PMID 26501338, 2015).
steatosis (56 papers, 2009 to 2025). Increased lipid within the cytoplasm of cells. "In the liver, CYP2E1 concentrations are strongly linked to morbidly obese subjects and elevated further in patients with steatosis while showing a decrease due to weight loss." (PMID 34835991, 2021). "Steatosis increases CYP2E1-mediated production of NAPQI, which causes mitochondrial deficits of GSH and enhanced activation of JNK." (PMID 33001859, 2020). "As ALD contains many types of histological forms, including steatosis, hepatisis, fibrosis, and cirrhosis, we then investigated the associations between CYP2E1 Pst I/Rsa I polymorphism and the risks of clearly defined alcoholic liver cirrhosis (ALC)." (PMID 23335995, 2013). "The authors concluded that oxidative stress develops in the livers of patients with steatosis and is exacerbated in patients with steatohepatitis associated with Cytochrome P450 2E1 (CYP2E1) induction." (PMID 23531105, 2013). "Increase in lipid peroxidation was accompanied by increased expression of CYP2E1 and ethanol induced CYP2E1 has been implicated in oxidative stress and steatosis." (PMID 22545783, 2012). "The CYP2E1, implicated in liver management of oxidative stress and steatosis, was significantly downregulated by luteolin, indicating that this flavonoid could be behind the antioxidant and antisteatotic effects of the AE." (PMID 39728509, 2024). "Indeed, in our HepG2 cell model of steatosis, the lipotoxic effect of OA stimulation was found to be associated with downregulation of PPARα and upregulation of CYP2E1 proteins." (PMID 38474427, 2024). "This might be indicative of the fact that increased lipid levels during steatosis might stimulate induction of liver fibrosis by the subsequent induction of CYP2E1 causing an increase ROS." (PMID 34360999, 2021). "This concerted pathogenic scenario triggered by CYP2E1-stabilization and sustained oxidative stress would account for the age-dependent progressive steatosis, nuclear pyknosis and hepatocyte ballooning observed at 9 months in CHIP−/−-livers relative to age-matched controls." (PMID 27406999, 2016). "Administration of CCl4 resulted in marked cloudy swelling, steatosis and necro‐inflammatory activity around the central vein, consistent with previous studies showing centrilobular necrosis due to high CYP2E1 expression in this region." (PMID 40542610, 2025). "Many issues need to be addressed before determining the roles of the CYP4A11-mediated 20-HETE and CYP2E1-related 19-HETE in steatosis, steatohepatitis, cirrhosis, and HCC, and possible therapeutic targets in the treatment of CLD." (PMID 40452921, 2024). "The increased expression of the CYP2E1 and CYP4A11 genes in steatosis, with a down-regulation of the CYP2E1 P450 and elevated CYP4A11 in the progression of MASLD indicate the differential role of these genes." (PMID 40452921, 2024). "Surprisingly, the expression of CYP2E1, a key enzyme in alcohol-induced oxidative stress and steatosis, decreased, in contrast to previous reports suggesting its role primarily in chronic alcohol consumption." (PMID 39120332, 2024). "In contrast, predominantly macrovesicular steatosis was correlated positively to the CYP2E1-activity." (PMID 36528753, 2022). "We also confirmed the strong positive correlation between steatosis severity and CYP2E1 activity as determined in the PNPH assay, see Fig. 5A3." (PMID 36528753, 2022). "The first hit produces steatosis; the second hit requires sources of oxidative stress, such as induction of CYP2E1 by a high-fat diet and an increase in the intrahepatic concentration of free fatty acids, which initiate significant lipid peroxidation." (PMID 33882064, 2021). "In CYP2E1 knock-in mice, ethanol administration led to the accumulation of lipid and steatosis as compared to CYP2E1 knockout mice." (PMID 33214856, 2020). "Acute alcoholism causes the elevation of CYP2E1, oxidative stress and lipogenic SREBP, which consequently lead to steatosis." (PMID 33214856, 2020).
steatosis (continued). "As expected from previous works, steatosis per se down-regulated the expression of several phase I and II XMEs of HepaRG cells, with some exceptions such as CYP2E1, ALDH1A3 and GSTM2P1 whose expression was increased." (PMID 29654281, 2018). "In NASH patients, hepatic CYP2E1 activity was increased and expression specifically localized to steatotic areas compared to patients with steatosis and healthy controls." (PMID 29936596, 2018). "The up-regulated expression of CYP2E1 and 4A was the important reason leading to lipid peroxidation damage of liver, insulin resistance and steatosis." (PMID 29534510, 2018). "These enhancement activities ranged between augmenting the inflammatory stress, oxidative stress, alteration of bile acid homeostasis, elevated cytochrome P450 2E1 (CYP2E1) expression, and both macro- and micro-steatosis." (PMID 29563874, 2018). "Hepatocyte lipid accumulation induces Cyp2E1, and the increase activity of Cyp2E1 in steatosis leads to tissue oxidative stress and production of reactive oxygen species." (PMID 26788255, 2016). "Following chronic (6 week) feeding with an ethanol-containing liquid diet, the Gclm KO mice were unexpectedly found to be protected against steatosis despite showing increased oxidative stress (as reflected in elevated levels of CYP2E1 and protein carbonyls)." (PMID 27403993, 2016). "Similar data about increased CYP2E1 expression in livers during development of steatosis were also reported." (PMID 26035647, 2015). "Of note, the joint effect of alcohol and cellular steatosis on autophagy required CYP2E1 activity in our in vitro model." (PMID 26497211, 2015). "Increased CYP2E1 activity correlates with the degree of steatosis and level of the inflammatory cytokines (e.g., TNF-α) involved in the pathology of NASH." (PMID 25406833, 2014). "Obese females with steatosis and NASH display elevated CYP2E1 protein levels and a positive correlation between the c2 allele of Rsa1/Pst1 polymorphisms in CYP2E1 and liver injury." (PMID 23346097, 2013). "Blocking alcohol dehydrogenase 1 (Adh1) and cytochrome P450 2E1 (Cyp2e1), the major enzymes that metabolize ethanol, prevented alcohol-induced steatosis and reduced induction of the UPR in the liver." (PMID 23798569, 2013). "In contrast to the many studies indicating a role of CYP2E1 in NAFLD and NASH, the decrease in CYP2E1 mRNA and protein from steatosis to steatohepatitis and fibrosis needs to be confirmed independently." (PMID 20300478, 2009). "This toxic solvent is metabolized by cytochrome p450, mainly by CYP2E1, producing free radicals such as CCl3* and CCl2* that affect lipid metabolism by inhibiting its transport out of hepatocytes and, in turn, increasing lipid synthesis, leading to steatosis." (PMID 38203648, 2023). "While the increased CYP2E1 and improved insulin resistance appear to stimulate each other, that may ultimately worsen the process of steatosis with the increase in oxidative stress." (PMID 35528835, 2022). "(d) CYP activity measured via EROD (CYP1A) and EMND (CYP3A) showed a negative association with steatosis parameters whereas PNHP (CYP2E1) showed a strong positive association." (PMID 36528753, 2022). "Few studies were investigating the steatosis-related modulation of CYP2E1 activity." (PMID 36528753, 2022). "Notably, alcohol and cellular steatosis also induced autophagy in a synergistic manner, and also this was mediated via CYP2E1." (PMID 26497211, 2015). "Similarly, lipid peroxidation, oxidative stress and pro-inflammatory gene expression as well as CYP2E1 levels and activity were synergistically induced by alcohol and steatosis." (PMID 26497211, 2015). "We speculate that autophagy-dependent processes such as mitophagy and lipophagy help to minimize ethanol-induced CYP2E1-dependent oxidative stress and therefore the subsequent liver injury and steatosis." (PMID 26501338, 2015).
steatosis (continued). "The significant changes in proteome profile in chronic ethanol binge were accompanied by a marked increase in liver injury as evidenced by enhanced steatosis, necrosis, increased 4-hydroxynonenal labeled proteins, CYP2E1 expression, and decreased histone H2AX phosphorylation." (PMID 22545783, 2012). "Disease mechanisms might involve (i) the initial ROS production due to lipotoxicity with the onset of steatosis; (ii) exacerbation of ROS generation due to concurrence of mitochondrial dysfunction, microsomal CYP2E1 induction, and inflammatory-cell activation." (PMID 23304111, 2012). "They demonstrated that inhibition of CYP2E1 prevented the increase in MDA and reduction in mtDNA levels, prevented alcohol induced steatosis and improved overall liver health." (PMID 39924874, 2025). "On the other hand, the gene expression of cytochrome P450 2E1 (CYP2E1), a contributor to oxidative stress in NAFLD, was found to be elevated in HepG2 cell model of steatosis." (PMID 38474427, 2024). "In contrast, mRNA levels of CYP2E1 and CYP3A4, major drug metabolizing genes, decrease in steatosis, MASH, and HCC." (PMID 40452921, 2024). "Furthermore, recent studies have shown that overexpression of CYP2E1 increases reactive oxygen species generation causes oxidative stress and leads to persistent stimulation of c-JNK signaling pathways, which leads to hepatocyte swelling and microvascular steatosis in people with NAFLD." (PMID 36677937, 2023). "The objective of our work was to study the impact of periportal steatosis on pericentral drug metabolism focusing on the important CYP isoforms CYP1A2, CYP2D6, CYP2E1, and CYP3A4." (PMID 36528753, 2022). "Compared to steatosis patients and healthy controls, hepatic CYP2E1 expression levels were elevated in NASH patients, and expression was localized in steatosis regions." (PMID 36552725, 2022). "The severity of steatosis was negatively correlated to the activity of CYP3A and CYP1A, but positively to the activity of CYP2E1." (PMID 36528753, 2022). "In our analysis, we correlated the extent of micro- respectively macrovesicular steatosis with the CYP activity and observed striking differences between the two patterns with respect to the activity of CYP2E1." (PMID 36528753, 2022). "Inflammation, steatosis, α-smooth muscle actin (α-SMA), and cytochrome P450 2E1 (CYP 2E1) expression increased significantly in the rats fed HFD and decreased in the rats administered by lycopene." (PMID 20953409, 2010). "In addition, this treatment seemed to play the role of metabolic protection being capable to restore the normal level of genes expression upregulated after steatosis treatment, between them RXRA, NR1H2, CEBPB, ADIPOR2, and CYP2E1." (PMID 36770927, 2023). "In addition, recent clinical studies have shown that the CYP2E1 inhibitor chlormethiazole reduces serum AST and ALT levels, and improves steatosis in patients with ALD." (PMID 36901774, 2023). "CYP2E1-positive cells were scattered throughout the lobule, usually (but not exclusively) following the distribution of steatosis." (PMID 38004588, 2023). "Based on nucleotide sequence homology to human CYP2E1 (43%) and inhibition by knock down experiments on APAP-induced steatosis, it is thought that zebrafish CYP2Y3 may be a functional homologue of human CYP2E1." (PMID 36835425, 2023). "The pattern of steatosis influenced the ex-vivo activity of CYP1A and CYP2E1." (PMID 36528753, 2022). "The severity of steatosis affected ex-vivo activity of CYP1A2 and CYP2E1." (PMID 36528753, 2022). "It has been shown that CYP2E1 (which has no role in ABT) is overexpressed in non-alcoholic steatosis." (PMID 33261113, 2020). "This is a paradox, because there was no steatosis and liver injury despite dose-dependent increases for CYP2E1 activity in EtOH-fed ADH+ deer mice." (PMID 31581705, 2019). "In the present study, low GSH-elicited CYP2E1 induction did not exacerbate liver damage or steatosis following chronic ethanol feeding." (PMID 27403993, 2016).
steatosis (continued). "Regardless of elevated CYP2E1 in the livers of betaine-supplemented ethanol-fed rat, indices of steatosis nor defects in the mitochondrial respiratory chain was observed in these animals." (PMID 22187660, 2012). "While it is well documented that CYP2E1 contributes to oxidative stress pathways in ALD and DILI, many reports have also demonstrated the critical role of CYP2E1 in MASLD through the production of ROS and LPOs; this may represent the second hit in the progression of steatosis to MASH." (PMID 38214802, 2024). "However, periportal steatosis did affect the activity of CYP1A, CYP2E1, and CYP3A." (PMID 36528753, 2022). "Therefore, irrespective of CYP2E1 overexpression; EtOH dose and hepatic ADH deficiency contribute to EtOH-induced steatosis and liver injury, suggesting a linkage between ER stress, dysregulated hepatic lipid metabolism and AMPK signaling." (PMID 31581705, 2019). "However, we can clarify for CYP2E1 that the expression pattern was not affected by steatosis, whereas the activity was positively correlated to the severity of steatosis reaching high significance (p < 0.001), when comparing severely steatotic with control samples." (PMID 36528753, 2022). "Thus, enhanced CYP2E1 did not differentiate bland steatosis from NASH, but could still play a role in disease progression." (PMID 29936596, 2018). "Long-term FF feeding in WT, but not Cyp2e1-null mice, produced typical features of NASH indicated by elevated steatosis (1st hit), nitroxidative stress, inflammation, liver injury and fibrosis." (PMID 28051126, 2017). "In contrast to the droplet analysis, the extent of microvesicular steatosis (%) was not significantly correlated to the results of EMND and PNPH reflecting mostly the activity of CYP3A and CYP2E1, see Fig. 5B1,B3, but showed a moderate negative correlation to the CYP1A activity, see Fig. 5B2." (PMID 36528753, 2022).